EGFR (epidermal growth factor receptor)
Diseases named in the same sentence as EGFR in open-access papers (continued):
Sharing a sentence is not in itself a finding about the gene and the disease.
lung cancer (continued). "Then we validated this pathway by cell line gene expression data from the CCLE and the same enrichment result was observed, suggesting the more probable formation of drug resistance of the young lung cancer group to EGFR-TKIs." (PMID 35096611, 2021). "We found that IFNγ simultaneously increased phosphorylation on STAT1 and STAT3 in EGFR-positive lung cancer, resulting in overexpression of PD-L1 (p < 0.05)." (PMID 34685495, 2021). "Small cell transformation of non‐small cell lung cancer (NSCLC) is commonly recognized as one of the resistance mechanisms to epidermal growth factor receptor (EGFR)‐tyrosine kinase inhibitors in EGFR‐mutant NSCLC treatment." (PMID 34622569, 2021). "ASOs targeting ARL4C (ASO-1316) showed decreased RAS-related substrate activity, inhibited cell proliferation and migration, and suppressed nuclear import of Yes-associated protein-1 (YAP-1) in lung cancer cell lines bearing KRAS and EGFR mutations." (PMID 33740988, 2021). "In conclusion, PD-L1 propels both migration and proliferation of EGFR+ lung cancer cells and reduces cell-to-cell and cell-to-matrix adhesion." (PMID 34038737, 2021). "The most vulnerable to antiproliferative activity of PRI-2191 was EGFR-mutant HCC827 lung cancer cell line, while KRAS-mutant cell lines were less sensitive." (PMID 33652978, 2021). "Apoptosis can be induced by stimulating the generation of ROS; however, such an effect was lower in high-EGFR-expressing lung cancer cells." (PMID 34071790, 2021). "Then, the in vitro cytotoxicity assay towards EGFR expressing lung carcinoma cell lines (A549 and A431) and T790M expressing lung cancer cell line (H1975) was conducted using MTT assay." (PMID 33921332, 2021). "An EGFR fragment and doxorubicin conjugated with MNPs increased the targeting ability and anti-cancer activity toward A549 cells (EGFR over-expressed cells present in human lung carcinoma cell line)." (PMID 34104817, 2021). "For example, in lung carcinoma cell lines A549 and H460, targeting EGFR, PI3K, and AKT enhances repair of DNA-DSBs and induces DNA-PKcs–dependent radiosensitization." (PMID 34356110, 2021). "EGFR signaling positively regulates miR-21 expression in lung carcinoma cell lines since the down-expression of miR-21 was induced by an EGFR-TKI." (PMID 34830377, 2021). "Taken together, this evidence suggests the EGFR-19 del lung cancer cells can transmit their EGFR phenotype to DCs, resulting in an immunosuppressive tumour microenvironment." (PMID 33143170, 2020). "In a study of six lung cancer patients with MET amplification and the epidermal growth factor receptor (EGFR) T790M mutation, 33 gefitinib-refractory lesions were collected at autopsy." (PMID 32369927, 2020). "RHOB which can have a dualistic role in cancer, was shown as conferring resistance to EGFR-tyrosine kinase inhibitors in lung cancer and frequently downregulated in aggressive lung cancer." (PMID 32733462, 2020). "SFN (stratifin) participates in the development and progression of lung cancer and stabilizes both EGFR and MET by interacting with ubiquitin-specific protease 8 (USP8)." (PMID 33023006, 2020). "In considering patients with lung cancer harboring mutant EGFR or HER2-positive breast cancer (BC) patients, these cancers are generally known to show a worse prognosis than other subtypes of the same cancer." (PMID 32280134, 2020). "The role of BIM in the induction of apoptosis of lung cancer cells, and its involvement in the primary resistance to EGFR‐TKIs of lung cancer patients, has attracted attention." (PMID 32508032, 2020). "Six different types of human lung cancer cells were used, all of which had faulty forms of EGFR, with three of the cell types showing drug resistance to current therapies." (PMID 32897190, 2020).
lung cancer (continued). "EGFR expression and NF-κB pathway activation have important roles in lung cancer progression and miR-146a and miR-155 have important roles in these pathways, and as their functions complement each other we decided to carry out a study on them." (PMID 33294082, 2020). "Our results confirmed the elevated ERβ5 levels in EGFR-mutant lung cancer cells; in contrast, ERβ1 was lowly expressed." (PMID 33585221, 2020). "Lung cancer cells expressing high DDX3X led to epidermal growth factor receptor (EGFR)-tyrosine kinase inhibitor (TKI) resistance and cancer stem cell-like phenotypes." (PMID 32326089, 2020). "This study reveals the role FBLN1 isoforms FBLN1C and FBLN1D as part of the CDM have in regulating EGFR activation and function in lung cancer cells." (PMID 32719793, 2020). "Even in early-stage lung cancer, if patients have GGN lesions, the EGFR gene mutation status should be investigated during follow-up." (PMID 32571419, 2020). "The study will recruit non‐small cell lung cancer patients (NSCLC) with slow progression after first‐line treatment with EGFR‐TKI drugs." (PMID 31918452, 2020). "Patients with “EGFR Wild Type/Low PD-L1 expression” lung cancer lack a first-line single drug therapy as they hardly respond to TKIs and immune checkpoint inhibitors." (PMID 32899191, 2020). "In this study, we have first established in vitro and in vivo EGFR-mutant lung cancer models with acquired resistance to EGFR TKIs, including the third generation TKI osimertinib." (PMID 33014814, 2020). "Epidermal growth factor receptor (EGFR) mutation‐positive non‐small cell lung cancer (NSCLC) patients benefit from EGFR tyrosine kinase inhibitors (TKIs), while some patients demonstrate a resistance to EGFR‐TKIs." (PMID 32744377, 2020). "Lipid rafts have been implicated in a variety of cellular processes, including signaling transduction of RTK 46, AXL 33 and c-MET 47 RTKs, by contributing to the pathophysiology of lung cancer and the acquired resistance to EGFR TKI." (PMID 33042262, 2020). "The target therapies of EGFR in lung cancer are based on small molecular tyrosine kinase inhibitors (EGFR-TKIs) that upon binding reduce intracellular signalling." (PMID 32107398, 2020). "Since EGFR signaling is linked to the activation of glycolysis, the inhibition of EGFR increased cell death via apoptosis in cancer such as lung cancer." (PMID 31940844, 2020). "This led to the issuance of FDA approval for osimertinib as the first-line therapy option for EGFR mutant lung cancer." (PMID 32549358, 2020). "A single-arm phase 2 trial for EGFR-positive lung cancer in EGFR TKI-untreated patients had been initiated, but was stopped during the interim analysis because of poor efficacy." (PMID 32283823, 2020). "The patient was discussed at the tumor board, and as surgery was not an option, the decision was made to treat the patient as stage IV EGFR lung cancer with a bilateral disease, and erlotinib therapy was immediately started." (PMID 32560187, 2020). "MiR-21 was proven to be aberrantly increased in Barrett’s oesophagus, which was further enhanced by the activated EGFR signaling pathway in lung cancers." (PMID 32903213, 2020). "Next, we evaluated the effects of BASP1 knockdown on EGFR inhibitors in different lung cancer cell lines that included EGFR-mutant and EGFR-WT cells." (PMID 33042262, 2020). "Epidermal Growth Factor Receptor (EGFR) is a known promoter of tumor progression and is overexpressed in lung cancers." (PMID 32719793, 2020). "It was observed that exosomes from HIV-infected T cells carrying HIV TAR RNA enter lung cancer cells through epidermal growth factor receptor (EGFR), stimulating cell proliferation and migration through activation of the ERK1/2 signaling pathway." (PMID 32641036, 2020).
lung cancer (continued). "PC-9 is commonly utilized in preclinical lung cancer research to evaluate the effects of chemotherapy in an EGFR-mutant model." (PMID 32264860, 2020). "Lastly, arsenic trioxide and EGFR TKIs reduce BASP1 expression and induce a synergistic inhibitory effect in lung cancer cells with acquired resistance to EGFR inhibitors." (PMID 33042262, 2020). "The immunotherapy based on antibodies against the Programmed Death-ligand 1 (PD-L1) and EGFR tyrosine kinase inhibitors are some targeted therapies in lung cancer." (PMID 32629823, 2020). "Lung cancer cells can carry mutations in a number of proto-oncogenes including KRAS, EGFR, BRAF, PI3K, MEK, and HER2, making targeted drug to be attractive treatment strategy." (PMID 33194645, 2020). "EGFR mutation is the most well-established driver mutation and the most important drug target in NSCLC that comprises approximately 85% of all lung cancer, and it was found a high EGFR mutation frequency (51.4% overall) in the tumors from Asian NSCLC patients." (PMID 32483443, 2020). "The potential mechanisms underlying these poor outcomes are the uninflamed phenotype of the microenvironment and the low immunogenicity of EGFR‐mutant lung cancer." (PMID 33075201, 2020). "In the KEYNOTE 024 phase III trial, pembrolizumab, an anti-programmed death 1 (PD1) antibody, showed better therapeutic effect than standard chemotherapy against EGFR wild type lung cancers overexpressing programmed death-ligand 1 (PD-L1)." (PMID 32899191, 2020). "Homoharringtonine (HHT)–loaded poly(lactic-co-glycolic acid)-SS-PEG is an epidermal growth factor receptor (EGFR) aptamer-modified PLGA targeted to the EGFR (which shows high expression in lung cancer cells)." (PMID 33363102, 2020). "The current anti-cancer strategies are based on the inhibition of a specific target playing a key role in tumor development [example: EGFR (lung cancers); HER2 (breast cancers); BRAF (melanoma)]." (PMID 32775327, 2020). "A post-hoc analysis of data from 32 patients pooled from LUX-Lung 2, LUX-Lung 3 and LUX-Lung 6 trials revealed clinical activity of afatinib against rare EGFR mutant (G719X, S786I, L861Q) lung cancers." (PMID 31562956, 2020). "We thus conducted a phase II multicenter, open‐label, single‐arm trial to evaluate the efficacy and safety of afatinib and bevacizumab combination therapy for EGFR gene mutant lung cancers previously treated with osimertinib." (PMID 32495514, 2020). "Phosphor-S6 protein overexpression was observed in EGFR-TKI sensitive or resistant lung cancer tissues with IHC analysis." (PMID 32913468, 2020). "For example, non–small cell lung cancer genotyping requires mutation pattern analysis of KRAS, EGFR, and BRAF." (PMID 32329738, 2020). "This study in identifying a role for matrix FBLN1 in regulating EGFR activation in NSCLC Calu-1 cells further adds to our understanding of this regulatory crosstalk in lung cancers." (PMID 32719793, 2020). "Our data showed arsenic exposure caused HB-EGF to stimulate EGFR phosphorylation (p-EGFR) at Tyr 1068 and confirmed HB-EGF was highly expressed in As-T cells and most tumor tissues samples of 35 lung cancer cases." (PMID 32695675, 2020). "We also observed a similar differential expression of LAMP1 and EGFR in eight patient lung cancers that harbored mutant versus two EGFR WT." (PMID 32194831, 2020). "The use of Src inhibitors such as dasatinib to overcome resistance to kinase inhibitors has previously been investigated in the context of mutant EGFR lung cancer." (PMID 32370101, 2020). "Innate immune resistance means that constitutive oncogenic signaling within tumor cells such as ALK-rearranged and EGFR-mutant lung cancer results in the upregulation of PD-L1 expression." (PMID 32325698, 2020). "In vitro cell model of acquired resistance to EGFR TKIs was established by culturing sensitive EGFR-mutant lung cancer HCC827 or PC9 cells in gefitinib or osimertinib with elevating concentration as we previously reported." (PMID 33014814, 2020).
lung cancer (continued). "In contrast, ectopic expression of BASP1 in lung cancer cells increased the levels of endogenous EGFR, phospho-EGFR, phospho-ERK, and phospho-AKT." (PMID 33042262, 2020). "In summary, previous studies indicated that blocking EGFR alone in lung cancer cannot prevent disease recurrence, because bypass routes inevitably instigate emergence of drug resistance." (PMID 32847130, 2020). "To further confirm the dysfunction of the microtubule network, we studied the distribution of the Golgi apparatus using an anti-GM130 antibody (GM130 is a cis-Golgi matrix protein) in multiple EGFR WT and mutant lung cancer cell lines." (PMID 32194831, 2020). "This was demonstrated in a number of studies, whereby we see the transfer of EGFR from lung cancer cells to endothelial cells, dendritic cells, macrophages and monocytes, activating pro-tumourigenic pathways in these low EGFR expressing recipient cells." (PMID 33143170, 2020). "Brigatinib, a dual ALK/EGFR inhibitor, is therefore being explored in clinical settings against lymphoma and lung cancer patients (NCT01449461)." (PMID 33262326, 2020). "Female patients are more prone to lung cancer, including LADC, and EGFR mutations are predictors of favorable responses to target treatments." (PMID 33050100, 2020). "EGFR has an important role in lung cancer and EGFR-tyrosine kinase inhibitors (EGFR-TKIs) are used successfully as targeted therapies." (PMID 33294082, 2020). "By focusing on the critical RTK in lung cancer, EGFR, we demonstrated that positive feedback between BASP1 and EGFR amplified the signaling in the lipid raft." (PMID 33042262, 2020). "Adjuvant chemotherapy or EGFR-TKI improves the survival of stage II–III lung cancer patients after surgery." (PMID 32802850, 2020). "A number of studies show that EGFR spatial distribution and stability are also crucial determinants in the regulation of lung cancer progression." (PMID 32694521, 2020). "On the bases of this background, the synergism between bone resorption and EGFR inhibitors in lung cancer patients deserves to be explored." (PMID 33282740, 2020). "The epidermal growth factor receptor (EGFR) localized to exosome membranes has been found to be a possible marker for lung cancer diagnosis." (PMID 33396739, 2020). "A study reported that treatment of lung cancer cell lines with TKIs enriches the ALDHbright stem-like cells through EGFR-dependent activation of Notch3 and inhibition of EGFR kinase activity leads to an increase in ALDHbright cells." (PMID 32293355, 2020). "TGFβ represses PDK4 expression, and PDK4 inhibition was sufficient to drive EMT and promote erlotinib resistance in epidermal growth factor receptor (EGFR) mutant lung cancer cells." (PMID 31822964, 2020). "Previous clinical studies have shown that bevacizumab in combination with chemotherapy or EGFR-TKIs provides a survival benefit for patients with advanced lung cancer." (PMID 33113888, 2020). "In vitro experiments with lung cancer cells showed down-regulation of EGFR- and NFkB-AKT-pathway leading to inhibition of proliferation, apoptosis induction and radiosensitization after Curcumin treatment." (PMID 32123256, 2020). "Osimertinib is recommended for T790M mutation‐positive advanced non‐small cell lung cancer (NSCLC) resistant to first‐ and second‐generation epidermal growth factor receptor (EGFR)‐tyrosine kinase inhibitors (TKIs)." (PMID 32129931, 2020). "Together, the data showed chronic drug treatment activated CAMK2A in lung cancer cells leading to increased resistance to both EGFR target therapy and cisplatin chemotherapy." (PMID 32483123, 2020). "EGFR-targeted therapies have well-established roles in the treatment of subgroups of lung cancer patients and colorectal cancer patients." (PMID 33024132, 2020). "KEAP1/NRF2 signalling regulates glutaminolysis metabolism by inhibition of glutaminase in KRAS-KEAP1 mutant lung cancer and regulates the sensitivity to EGFR-TKI." (PMID 33186371, 2020).
lung cancer (continued). "Our finding that arsenic activates EGFR in lung cancer is supported by reported observations of EGFR activation by either 100 μM arsenite or 800 μM arsenate in another keratinocyte type." (PMID 32695675, 2020). "EVs isolated from tumour tissue of lung cancer patients and lung tissue from patients with chronic inflammation were found to be 80% and 2% positive for EGFR staining, respectively." (PMID 33143170, 2020). "In tumors with normal distribution of TIL, the cytotoxic effect of T lymphocytes in vivo can be restored by downregulating the expression of PD‐L1 in EGFR‐TKI drug‐resistant lung cancer." (PMID 32875727, 2020). "Genetic alterations in MAPK/ERK pathway are very common in non‐small cell lung cancer (NSCLC), especially mutations found in the upstream members, EGFR and KRAS, which account for 70% or more of all known driver mutations." (PMID 32757330, 2020). "Since the EGFR gene mutations are related to the EGFR-TKI efficacy, patients with advanced lung cancer are recommended to have their tumors tested for the EGFR sensitizing and resistance mutations." (PMID 32093010, 2020). "Rare mutations in EGFR account for ̃15% of EGFR mutations in NSCLC, amounting to around 30,000 diagnoses per year owing to the high prevalence of lung cancer." (PMID 31562956, 2020). "Non-small-cell lung cancer (NSCLC) accounts for approximately 70-80% of all lung cancers 2 and oncogenic activation of receptor tyrosine kinases (RTKs), such as epidermal growth factor receptor (EGFR), is especially relevant for this disease." (PMID 33042262, 2020). "Epidermal growth factor receptor (EGFR) mutation is one of the most common genetic disorders in non‐small cell lung adenocarcinoma, which is the most common lung cancer subtype worldwide, resulting in an ideal therapeutic target." (PMID 33015988, 2020). "Metformin overcomes IL-6-induced EGFR-TKI resistance in TKI-sensitive lung cancer cells through the inhibition of STAT3 and AKT phosphorylation and the enhancement of AMPK activation." (PMID 32041944, 2020). "The aim of this study was to investigate the effects that AuNR targeting to EGFR positive lung cancer cells has on both CW and PW laser treatment." (PMID 32635387, 2020). "With EGFR overexpression in lung cancers known to be correlated with poor prognosis, a significant increase in EGFR transcript levels was seen in the TCGA pan lung cancer (∼1.3 fold) and LUSC (∼1.7 fold) [datasets]." (PMID 32719793, 2020). "The most studied proliferation markers and, consequently, the most targeted molecules related to cellular proliferation in lung cancer imaging are EGFR and Ki-67." (PMID 33198090, 2020). "Currently, chemotherapy is a standard therapy for lung cancer patients with EGFR exon 20 insertions due to the limited clinical benefits of TKI treatments observed in previous studies." (PMID 32412152, 2020). "Considering all of the 33 deregulated miRNAs, significantly enriched pathways included EGFR and TGFβ signal transduction, which are known to be involved in lung cancer development and progression." (PMID 32971741, 2020). "In one study, erlotinib-resistant EGFR mutant lung cancer cells showed increased MCL-1 expression, and were sensitive to EGFR TKIs when combined with navitoclax." (PMID 32131385, 2020). "The treatment options for EGFR-mutated and ALK-rearranged NSCLCs are distinctly different from those of lung cancer that lacks actionable mutations." (PMID 32030321, 2020). "Osimertinib and rociletinib, two anti-cancer drugs for lung cancer, work by shutting off mutant EGFR, which initially kills cancerous tumors, but the tumors rewire and activate Aurora kinase A, becoming cancerous growths again." (PMID 32795325, 2020).